EGFR (epidermal growth factor receptor)
Diseases named in the same sentence as EGFR in open-access papers (continued):
Sharing a sentence is not in itself a finding about the gene and the disease.
lung adenocarcinoma (continued). "Similar lineage transitions are observed in other cancers treated with targeted therapies, for example, EGFR-, ALK- and KRASG12C-mutant lung adenocarcinoma, underscoring the broad relevance of lineage plasticity in tumor progression and therapy resistance." (PMID 39394434, 2024). "In a previous study, we showed that EGFR-TKI combined with craniocerebral radiotherapy improved iPFS, OS and PFS in patients with EGFR-mutant lung adenocarcinoma with BM." (PMID 38478262, 2024). "In lung adenocarcinoma, CLDN-2 exhibits high expression through an EGFR/MEK/ERK/c-Fos pathway, and its overexpression has been linked to increased proliferation." (PMID 38338691, 2024). "The PET group used the best radiomics characteristics of PET and EGFR, SUVmax, SUVpeak, Volume, and TLG to construct different machine learning models to predict brain metastasis of lung adenocarcinoma." (PMID 38605303, 2024). "Studies suggest that in EGFR wild-type NSCLC patients, conventional EGFR-TKI treatments are ineffective, but using EZH2 inhibitors (such as GSK343 or DZNep) sensitizes lung adenocarcinoma cells to gefitinib." (PMID 38525426, 2024). "The EGFR L747P mutation responsiveness to EGFR‐TKIs is unknown, but case reports indicate that lung adenocarcinoma patients with the EGFR L747P mutation were not sensitive to first‐ and third‐generation EGFR‐TKIs but were sensitive to second‐generation EGFR‐TKIs." (PMID 38572952, 2024). "Afatinib is an irreversible inhibitor of the ERBB receptor family (including EGFR, HER2, ERBB3, and ERBB4), and has been approved for the treatment of advanced lung adenocarcinoma." (PMID 39406703, 2024). "Here, we show that SOS2 modulates the threshold of epidermal growth factor receptor (EGFR) signaling to regulate the efficacy of and resistance to the EGFR tyrosine kinase inhibitor (EGFR-TKI) osimertinib in lung adenocarcinoma (LUAD)." (PMID 38073064, 2024). "For the analysis, we focused on agents targeting EGFR and BRAF that are used in lung adenocarcinomas and melanomas (LUAD and SKCM), respectively." (PMID 39160568, 2024). "Immunohistochemistry (IHC) analysis revealed a positive correlation between phospho-EGFR levels and CBL-c expression in lung adenocarcinoma." (PMID 39130630, 2024). "Previous studies demonstrated that HPV infection was found more frequently in lung adenocarcinoma patients with EGFR gene mutations than in patients without mutations, suggesting that the viral protein E6 regulates the inhibitors of apoptosis of the EGFR/PI3K/AKT signaling pathway." (PMID 39205175, 2024). "EGFR and KRAS are two of the most important driver genes in lung adenocarcinoma, accounting for a large proportion of cases." (PMID 39639005, 2024). "In lung adenocarcinoma patients, PDPN-positive CAFs have been shown to induce resistance to gefitinib, an epidermal growth factor receptor/tyrosine kinase inhibitor (EGFR-TKI) used to treat advanced NSCLC." (PMID 39403603, 2024). "This study analyzed the effects of EGFR-TKI targeted combined chemotherapy on immune function, tumor markers and oxidative stress level in patients with stage-IV lung adenocarcinoma." (PMID 37250563, 2023). "With more and more targeted drugs clinical applications, such as Epidermal Growth Factor Receptor (EGFR)–Tyrosine Receptor Inhibitors (TKIs), the overall survival time of patients with lung adenocarcinoma, was significantly prolonged." (PMID 35614541, 2023). "Before the emergence of radiomics, the clinical characteristics of patients with lung adenocarcinoma were frequently applied to predict EGFR mutation status, and multiple clinical characteristics (e.g., female, non-smoker, and adenocarcinoma histology) were related to EGFR mutations." (PMID 38094613, 2023).
lung adenocarcinoma (continued). "BC was highly expressed in 428 patients with lung adenocarcinoma (LUAD) and high BC expression correlated with reduced efficacy of EGFR‐TKI therapy." (PMID 36650118, 2023). "In addition to anti-EGFR antibodies, brigatinib can also be combined with the vascular endothelial growth factor (VEGF) inhibitor bevacizumab, in combination with osimertinib to effectively combat lung adenocarcinoma with EGFR L858R-T790M-cis C797S triple mutation." (PMID 37041601, 2023). "For example, among the top three exclusively mutated gene pairs are BRAF and NRAS in skin cutaneous melanoma (p = 1.1 × 10–44), KIT and PDGFRA in gastrointestinal stromal tumour (p = 3.3 × 10–37), and EGFR and KRAS in lung adenocarcinoma (p = 6.6 × 10–29)." (PMID 37550388, 2023). "Previous data indicated that uPAR induced the resistance to anti-cancer agents via the EGFR/p-AKT signaling pathway, as observed in gefitinib-resistant human lung adenocarcinoma cells and vemurafenib-resistant melanoma cells." (PMID 37895906, 2023). "In the present study, the EGFR tyrosine kinase inhibitor AG1478 prevented the upregulation of CLDN-2 at the protein and mRNA levels induced by EGF in lung adenocarcinoma cell line A549." (PMID 36961882, 2023). "To further analyze the possible pathways and mechanisms of MMP11 affecting immune response in EGFR mutant lung adenocarcinoma, we analyzed the differential genes between high and low MMP11 expression groups in EGFR mutant lung adenocarcinoma." (PMID 36756152, 2023). "However, for the 12 trials enrolling patients with non-specified NSCLC histology but with mandatory presence of EGFR mutations (n = 6), ALK rearrangements (n = 5), or KRAS mutations (n = 1), the vast majority of enrolled patients (> 90% for each study) had a diagnosis of lung adenocarcinoma." (PMID 37400832, 2023). "Here, we show that SOS2 modulates the threshold of epidermal growth factor receptor (EGFR) signaling to regulate the efficacy of and resistance to the EGFR-TKI osimertinib in lung adenocarcinoma (LUAD)." (PMID 37425733, 2023). "This fact is particularly relevant in lung adenocarcinoma, since some of the oncodrivers of this histological subtype are HSP90 clients such as EGFR, HER2, MET, BRAF, and the EML4-ALK fusion protein." (PMID 37762133, 2023). "We consulted the RNA-seq datasets of the TCGA database and noticed CNOT3 expression was positively correlated with the expression of some ErbB family of receptor tyrosine kinases such as EGFR, ErbB-2 (neu, HER2) and ErbB-3 (HER3) in lung adenocarcinoma." (PMID 37919290, 2023). "Also, studies on breast, gastric, and colorectal cancers have stated that serum soluble E-cadherin level is inversely correlated with E-cadherin expression in tissues, but whether this correlation applies to EGFR-mutant lung adenocarcinoma needs further investigation." (PMID 37340370, 2023). "IHC analysis of EGFR and thyroid transcription factor-1 (TTF-1), a sensitive marker of primary lung adenocarcinomas, showed significant enhancement in LC-HFD mice compared with LC-RD mice, which confirmed the H&E results." (PMID 37929799, 2023). "EGFR-tyrosine kinase inhibitors (EGFR-TKIs) have been listed as the preferable standard of care in EGFR-mutant NSCLC patients, in particular for lung adenocarcinoma (LUAD)." (PMID 37361601, 2023). "In lung adenocarcinoma, the co-high expression of ARF6, GEP100 and p-EGFR obviously predicts a bad prognosis." (PMID 37716993, 2023). "DSG2 has been previously reported to facilitate EGFR activity; DSG2/EGFR interaction has demonstrated importance in the development of SCC, colon cancer, and lung adenocarcinoma." (PMID 38188287, 2023). "Aberrant activation of EGFR downstream signaling pathways, mainly including PI3K/AKT/mTOR and MAPK/ERK, is a crucial trigger for the initiation of lung adenocarcinoma." (PMID 37239162, 2023).
lung adenocarcinoma (continued). "CTC counts correlated to tumor progression in patients with early lung adenocarcinoma and successfully detected typical mutant genes (Notch1, IGF2, EGFR, and PTCH1) and genes in smokers as predictive biomarkers." (PMID 37371825, 2023). "The advent of immune checkpoint blockade (ICB) has led to significantly improved disease outcome in lung adenocarcinoma (ADC), but response of ALK/EGFR-positive tumors to immune therapy is limited." (PMID 34125345, 2022). "However, the WJOG-8715 L trial compared osimertinib plus bevacizumab vs. osimertinib alone, and the combination treatment did not lead to prolonger PFS in patients with advanced lung adenocarcinoma with EGFR T790 M mutation (HR = 1.44, 95% CI: 0.83–2.52; P=0.20)." (PMID 36312218, 2022). "In lung adenocarcinoma, METTL7B was found to mediate the resistance to EGFR-tyrosine kinase inhibitors (EGFR-TKIs) via methylating GPX4, HMOX1, and SOD1 mRNA." (PMID 35804965, 2022). "On the other hand, retinoic acid affects the growth of lung adenocarcinoma by inducing cell differentiation and inhibiting proliferation after the activation of GATA6, and the inhibition of Wnt and EGFR." (PMID 36101460, 2022). "To investigate effects of Huaier on EGFR mutant NSCLC cells, we employed PC9 cell line, an EGFR 19 exon deletion mutant lung adenocarcinoma cell line that are highly dependent on EGFR activation, for further study." (PMID 35470770, 2022). "In lung adenocarcinoma, SKA3 promoted metastasis by binding to EGFR and activating the PI3K/AKT signaling pathway." (PMID 36439516, 2022). "In lung adenocarcinoma, EGFR mutant tumor tended to show lower HK2 expression than EGFR wild type tumor (P = 0.079)." (PMID 36320008, 2022). "A study demonstrated that the lncRNA LOC389641 played an oncogenic role in lung adenocarcinoma through suppressing autophagy by reducing the expression of autophagy-related proteins, p-AMPK and LC3B via EGFR/MET/STAT3 signalling." (PMID 35379783, 2022). "assessed 133 patients with brain metastases arising from EGFR-mutant lung adenocarcinoma who received upfront gamma knife SRS and subsequently were administered EGFR tyrosine kinase inhibitors." (PMID 35311078, 2022). "After culture in a defined small-molecule-based serum-free medium in a nonadhesive culture system, floating spheres with round and smooth contours were successfully obtained from A549 (EGFR wild-type, KRAS-G12S) human lung adenocarcinoma cells." (PMID 35956408, 2022). "Histological transformation of lung adenocarcinoma into SCLC is a rare event, which has been described as a key resistance mechanism to tyrosine kinase inhibitor (TKI) treatment in around 5% EGFR-mutant and few ALK-rearranged NSCLC cases." (PMID 35511434, 2022). "Here we show that Daidzein synergizes with Gefitinib via ROS mediated c-Jun nuclear translocation and suppresses EGFR-STAT/AKT/ERK signalling axis to induce a G0/G1cell cycle arrest and apoptosis in A549 and H1975 lung adenocarcinoma cells." (PMID 35813479, 2022). "Activation of epidermal growth factor receptor (EGFR) tyrosine kinases can promote EMT and inhibit apoptosis in lung adenocarcinoma." (PMID 35935969, 2022). "HER2 amplification also has been recognized as a rare resistant mechanism in lung adenocarcinoma occurring in 1–2% of total cases in patients and tends to be up to 13% in NSCLC patients with resistance to EGFR-TKIs." (PMID 35163777, 2022). "In conclusion, our study demonstrated that platelets in the high D-dimer plasma were activated and induced EGFR TKI resistance through Src-mediated EGFR transactivation, Akt activation, and EMT in patients with mutant lung adenocarcinoma." (PMID 35756605, 2022). "Therefore, upfront BRT may offer an intracranial PFS benefit in patients with BM from lung adenocarcinoma, especially in patients without EGFR (19 or 21) mutation, but cannot provide an additional OS benefit." (PMID 35069906, 2022).
lung adenocarcinoma (continued). "The results provided molecular evidence in our prior studies showing better responses to platinum-based chemotherapy in lung adenocarcinoma patients with HPV infections and EGFR expression." (PMID 36358752, 2022). "In another study, bevacizumab combined with EGFR tyrosine kinase inhibitor reduced circulating S100A9 positive MDSCs and improved progression-free survival in patients with EGFR mutant lung adenocarcinoma." (PMID 35122833, 2022). "Also, no other common lung adenocarcinoma driver mutations such as EGFR or ALK were detected." (PMID 35864317, 2022). "We have reported that SP-D directly binds to the N-glycans of EGFR, and downregulates the binding of EGF to EGFR and downstream signaling in human lung adenocarcinoma cells." (PMID 35089466, 2022). "Our findings show that EGFR is clustered before and after EGF binding, consistent with observations from AFM studies using EGF-coated tips which imaged human lung adenocarcinoma cells from the A549 cell line, known to have high EGFR expression." (PMID 35612280, 2022). "To examine the importance of YAP/TAZ activation under EGFR in HNSCC and lung adenocarcinoma cells, we genome edited the LATS1 and LATS2 genes to activate YAP/TAZ in both cells harboring EGFR alterations." (PMID 34725466, 2021). "In silico clinical correlation analysis using the Cancer Genome Atlas Lung Adenocarcinoma dataset revealed a positive correlation between LANCL2 and EGFR expression and an inverse relationship between LANCL2 gain-of-function and survival in LUAD patients." (PMID 33568630, 2021). "Previously, we reported the correlations between tumor size and epidermal growth factor receptor (EGFR) expression, as well as between EGFR and progesterone receptor expression in NNK-induced female mouse lung adenocarcinomas." (PMID 34200786, 2021). "However, the EGFR mutation is not the only genetic alteration in lung adenocarcinomas with MLCs." (PMID 34234879, 2021). "In summary, the current study has demonstrated that DR4 expression is a poor prognostic factor in human lung adenocarcinoma and revealed a previously undiscovered anti-apoptotic function of DR4 in the induction of apoptosis by osimertinib and other EGFR-TKIs." (PMID 33664875, 2021). "Treatment with gefitinib as an EGFR inhibitor suppressed MAPF-induced endothelial migration and partially attenuated endothelial proliferation in both wild-type and mutant EGFR lung adenocarcinoma." (PMID 34680445, 2021). "In lung adenocarcinoma, reduced DNAJA3/Tid1 protein levels are correlated with poor overall survival and increased EGFR levels." (PMID 34948322, 2021). "This large-scale dataset revealed that the Class I-presented immunopeptidome was suppressed in two third-generation EGFR TKI, osimertinib-resistant lung adenocarcinoma cell lines compared to their isogenic TKI-sensitive counterparts." (PMID 34638461, 2021). "We set to establish an appropriate preclinical orthotopic mouse model using luciferase tagged lung adenocarcinoma PC9 cells, harboring EGFR TKI sensitive exon 19 deletion, injected through a tail vein to model and extend the implications of the ADAURA trial." (PMID 33993094, 2021). "In human lung adenocarcinoma A549 cells, MMP secretes epidermal growth factor, activates the EGFR-ERK signaling pathway, and promotes the expression of claudin-2, thus promoting tumor colonization (ciardiello and Tortora, 2008)." (PMID 34178945, 2021). "EGFR and HDAC1 were present in the membrane-bound organelle and nuclear fractions of lung adenocarcinoma cell lines." (PMID 33976119, 2021). "The postoperative pathology showed lung adenocarcinoma (pT2aN1M0, stage IIA) with EGFR exon 19 deletion." (PMID 33725888, 2021). "To this end, we measured CD8 expression as a marker of tumour infiltrating CD8 T-cells in NSCLC lung adenocarcinoma (LUAD) samples deposited in the TCGA database, and correlated CD8 with EGFR expression." (PMID 35052732, 2021).
lung adenocarcinoma (continued). "Therefore, we hypothesized that the lower impact of EphB4 on cell proliferation in EGFR mutation-negative lung adenocarcinoma could be due to the potential influence of various other factors related to smoking." (PMID 34445227, 2021). "The first set of experiments was conducted on three K-Ras mutant (A549, H460, and H23) and three EGFR mutant (H1650, PC9 and H1975) lung adenocarcinoma cell lines." (PMID 34359807, 2021). "More peptides were identified from the lung adenocarcinoma cell lines, PC9 and H1975, compared with the EGFR-mutant tumor, NCI-RA007, and the melanoma patient–derived cell lines." (PMID 34391887, 2021). "Moreover, direct PCR sequencing was useful in identifying EGFR and KRAS mutations in formalin-fixed and paraffin-embedded (FFPE) samples from primary tumors and pleural metastasis, this latter including PF cell blocks and pleural biopsies of 37 lung adenocarcinoma patients." (PMID 34199799, 2021). "In particular, patients diagnosed with lung adenocarcinoma and MET amplification showed acquired resistances when treated with epidermal growth factor receptor (EGFR) inhibitors like Gefitinib or Erlotinib, regardless of EGFR mutation status." (PMID 34733418, 2021). "Lung adenocarcinoma patients with intraoperatively-confirmed occult pleural dissemination (M1a), who hospitalized in the Department of Thoracic Surgery in Fudan Shanghai Cancer Center from May 2008 to December 2017 and received EGFR-TKIs therapy, were enrolled." (PMID 33954108, 2021). "Lung adenocarcinoma patients with positive CLDN1 expression had poorer prognosis than negatives, and combination of CLDN1/Ras/EGFR was reported as a valuable independent prognostic factor." (PMID 33597819, 2021). "The data above together indicated that the upstream activating mechanisms, such as EGFR, can activate DRP1 in lung adenocarcinoma cell lines through ERK and AKT signaling." (PMID 33152171, 2021). "In lung adenocarcinomas, the S1P-S1P3 signaling upregulates EGFR and enhances EGFR-mediated carcinogenic activities contributing to tumorigenesis or progression of lung adenocarcinomas." (PMID 34201962, 2021). "The application of tyrosine kinase inhibitors against specific gene targets (EGFR, ALK and ROS1) has revolutionized the treatment for lung adenocarcinoma." (PMID 33738250, 2021). "Another study performed massive parallel sequencing on 183 lung adenocarcinoma patients and identified complex genomic rearrangements that generated a novel deletion of exons 25 and 26 in the CTD of EGFR." (PMID 34610265, 2021). "Overexpression of RhoV in lung adenocarcinoma promotes the progression and EGFR-TKI resistance, suggesting RhoV is a promising prognosis and therapeutic target of lung adenocarcinoma." (PMID 33767988, 2021). "To further explore the value of BMP5 in clinical treatment, we first analyzed the correlation of mRNA expression between BMP5 and EGFR/STK11, which are critical molecular in targeted therapy and immunotherapy of lung adenocarcinoma." (PMID 34745928, 2021). "In lung adenocarcinoma (LAC), Epidermal growth factor receptor (EGFR) is one of the most common driver genes and can be detected in 40%-50% of Asian patients." (PMID 34485120, 2021). "Osimertinib, a third generation EGFR TKI, has shown great efficacy in EGFR mutant lung adenocarcinoma; however, patients treated with osimertinib eventually develop acquired resistance." (PMID 34638461, 2021). "The epidermal growth factor receptor (EGFR) is known to be overexpressed in several cancer types, such as lung adenocarcinoma, head and neck squamous cell carcinoma, and colorectal carcinoma." (PMID 33925941, 2021). "The frequent EGFR mutation may be due to the lung adenocarcinoma itself rather than the MLCs." (PMID 34234879, 2021). "In total, 28 EGFR-mutant lung SCC, 41 EGFR-mutant lung adenocarcinoma, and 40 EGFR wild-type lung SCC patients were included." (PMID 34195081, 2021).